MMP1 (matrix metallopeptidase 1)
Diseases named in the same sentence as MMP1 in open-access papers (continued):
Sharing a sentence is not in itself a finding about the gene and the disease.
tuberculosis (24 papers, 2009 to 2025). A chronic, recurrent infection caused by the bacterium Mycobacterium tuberculosis. "Previous studies have identified MMP-1 activity, from multiple cell types, including respiratory epithelial cells, as having a key role in tuberculosis-associated tissue destruction." (PMID 29988449, 2018). "Multivariate analysis of main and joint effects of MCP-1 and MMP-1 tuberculosis susceptibility genotypes in Peruvians." (PMID 20111728, 2010). "Multivariate analysis of main and joint effects of MCP-1 and MMP-1 tuberculosis susceptibility genotypes in Mexicans." (PMID 20111728, 2010). "Because integrin αVβ3 was increased in our cellular model of tuberculosis and its activation was associated with increased MMP-1 and -10 secretion, we next investigated whether this might be happening in TB patients." (PMID 28646039, 2017). "In this longitudinal analysis of patients with tuberculosis receiving treatment, we found that concentrations of plasma MMP-1, MMP-8, MMP-10, and PIIINP decreased with effective tuberculosis treatment over 2 months." (PMID 35510939, 2022). "We applied BB94, which is a broad spectrum for MMPs including MMP-1/9, to further explore direct effect of MMP-1/9 on tuberculosis." (PMID 35095838, 2021). "The signalling pathways driving MMP-1 expression have been described, but relatively little is known about regulatory pathways that limit immunopathology in tuberculosis." (PMID 28570642, 2017). "On the other hand, MMP-1 is the main protease for tissue destruction and remodeling in tuberculosis." (PMID 26367274, 2015). "Proportion of cells expressing high levels of MCP-1 and MMP-1 in lymph nodes from cases of tuberculosis carriers of -2518 MCP-1 and -1607 MMP-1 two-locus genotypes A." (PMID 20111728, 2010). "In a recent study, it was shown that the levels of both HO-1 and MMP-1 are significantly elevated in the plasma of active TB patients compared to healthy controls and individuals with latent tuberculosis infection." (PMID 33530574, 2021). "In studies involving adult pulmonary tuberculosis (TB) patients, increased levels of matrix metalloproteinases (MMPs), including MMP-1, 2, 3, 7, 8, and 9, have been observed in various biological fluids such as sputum, pleural fluid, and bronchoalveolar lavage (BAL) fluids." (PMID 40558582, 2025). "Because MMP-1 is a key mediator of M. tuberculosis–associated immunopathology, we investigated the role of components of the ECM on the regulation of MMP-1 gene expression and secretion by primary human monocytes in TB." (PMID 28646039, 2017). "Monocyte-microglial network-dependent MMP-1 and MMP-3 gene expression and secretion are dependent upon p38 MAPK in tuberculosis." (PMID 23978194, 2013). "Tuberculosis (TB) of the central nervous system (CNS) is characterized by extensive tissue inflammation, driven by molecules that cleave extracellular matrix such as matrix metalloproteinase (MMP)-1 and MMP-3." (PMID 23978194, 2013). "In plasma, MMP-1, MMP-8, and procollagen III N-terminal propeptide (PIIINP), a matrix degradation product released during collagen turnover, are elevated in patients with tuberculosis compared with healthy or respiratory symptomatic controls." (PMID 35510939, 2022). "MMP proteins have been linked to leukocyte migration and the progression of granuloma formation during tuberculosis; MMP1 and MMP14 gene products are key for the destruction of collagen and alveolar destruction with increased expression of MMP14 found in the sputum of tuberculosis patients." (PMID 29343690, 2018). "Increased MMP-1 availability and activity early in M. tuberculosis infection may destabilize granuloma formation, in particular the correct organization of new granulomas, promoting spread of the infection and progression to active TB." (PMID 20111728, 2010).
tuberculosis (continued). "Our findings show that M. tuberculosis stimulation of PBMCs differentially increased the transcript levels for MMP-1, MMP-7, MMP-10, and TIMP-1 genes in paradoxical TB-IRIS participants in 24 h cultures (pcorr ≤ 0.05) compared with non-IRIS controls." (PMID 24136296, 2014). "Taken together the present work shows that, in M. tuberculosis–infected monocytes, increased integrin αVβ3 expression, which is also found in TB patients, promotes increased monocyte adhesion to ECM, and upregulates MMP-1 and -10 secretion, which in turn will drive ECM breakdown." (PMID 28646039, 2017). "MMP-1, MMP-3, MMP-7, and MMP-10 gene expression was analyzed by quantitative RT-PCR in M. tuberculosis stimulated PBMCs from 16 TB-IRIS participants treated with prednisone therapy compared with 12 patients who were placebo treated over 4 weeks of prednisone versus placebo treatment." (PMID 24136296, 2014). "Sputum MMP-1 and MMP-8 are significantly elevated in patients with tuberculosis at diagnosis compared with controls, irrespective of HIV serostatus." (PMID 35510939, 2022). "In patients without HIV infection, elevated sputum MMP-1, MMP-2, MMP-3, and MMP-8 concentrations decrease after just 2 weeks of tuberculosis treatment." (PMID 35510939, 2022). "Upon stimulation with M. tuberculosis for 6 h, several of the MMP transcripts including MMP-1, MMP-3, MMP-7, and MMP-10 (pcorr ≤ 0.05) increased in abundance in both TB-IRIS and non-IRIS patients when compared with those of unstimulated cultures." (PMID 24136296, 2014). "However, after 24 h of stimulation with M. tuberculosis, MMP-1, MMP-7, and MMP-10 transcripts were observed to be significantly higher in the PBMC cultures of TB-IRIS as compared with those of non-IRIS patients (pcorr = 0.02, pcorr = 0.05 and p = 0.01, respectively)." (PMID 24136296, 2014).
asthma (23 papers, 2012 to 2026). "MMP-1 is a collagenase that is upregulated in patients with asthma, and its expression is potentially associated with airway narrowing and asthma symptoms." (PMID 40981103, 2025). "A recent study has shown that MMP1 is associated with bronchial hyperresponsiveness and asthma exacerbation severity." (PMID 31889146, 2019). "In support of activation of MMPs by tryptase, mast cell tryptase has been shown to activate lung MMP1 from pro-MMP1 in asthma and increase disease severity." (PMID 37663654, 2023). "In bronchial epithelial cells, AhR agonists led to the upregulation of MMP2, MMP9, and MMP1 and proposed to contribute to airway remodeling in asthma and chronic obstructive pulmonary disease." (PMID 33488929, 2020). "The levels of MMP1 in individuals with asthma correlate with bronchial hyperresponsiveness (BHR) and exacerbation of disease." (PMID 32086776, 2020). "According to other studies, MMP-1 expression is believed to be stimulated by type 2 cytokines and thereby contributes to airway hyper-responsiveness in allergen-induced asthma." (PMID 30834110, 2019). "MMP1, MMP3, MMP8, and MMP12 levels were associated with severe asthma and were correlated positively with sputum IL-5 levels but negatively with IL-13 levels." (PMID 26851968, 2016). "We then compared MMP-1 expression in ASM cells obtained from six patients with asthma and six controls." (PMID 24587395, 2014). "Asthma derived ASM cells produced more collagen-I under basal conditions than normal cells and ECM deposited by asthma derived cells had a greater capacity to induce MMP-1 secretion than control ECM." (PMID 24587395, 2014). "As tenascin-C strongly induced MMP-1 expression and activity and is expressed in the airways of patients with asthma, tenascin-C was studied in detail." (PMID 24587395, 2014). "Our findings would suggest that increased MMP-1 in asthma biopsies and asthma ASM cells is the result at least in part of abnormal deposition of ECM." (PMID 24587395, 2014). "Despite the potential importance of MMP-1 in asthma, few studies have examined its regulation in ASM cells." (PMID 24587395, 2014). "Asthma derived ASM had higher basal expression of MMP-1 and higher tenascin-C stimulated MMP-1 levels than control ASM cells." (PMID 24587395, 2014). "In patients with asthma there was strong expression of both tenascin-C and MMP-1 in the sub-epithelial basement membrane and smooth muscle bundles." (PMID 24587395, 2014). "This is consistent with our findings that asthma derived ASM cells produce more MMP-1 and a functionally different ECM." (PMID 24587395, 2014). "Collagen-I and tenascin-C induced MMP-1 protein expression, which for tenascin-C, was greater in asthma derived ASM cells." (PMID 24587395, 2014). "The data presented here demonstrate that the production and activation of MMP-1 by ASM is regulated by ECM proteins present in the airways of patients with asthma." (PMID 24587395, 2014). "Further, ECM from asthma derived ASM cells stimulated MMP-1 expression to a greater degree than ECM from normal ASM." (PMID 24587395, 2014). "The proteins that are regulated by LPS and were previously shown to be implicated in asthma and in ASM proliferation also include the upregulation of matrix-metalloproteinase-1 (MMP-1) and Abelson interactor 1 (Abi1) and the downregulation of insulin-like growth factor-binding protein 2 (IGFBP-2)." (PMID 36359743, 2022). "Interestingly, FP alone significantly reduced several pro-inflammatory genes related to ASM and asthma, including IL-6, MMP1, PTGS2, and TNFSF15." (PMID 35578269, 2022). "Other MMPs, including MMP-1, -2, -3, or -12, are also studied as being involved in asthma." (PMID 31547356, 2019). "In a study using airway smooth muscle (ASM) cells from asthma and control patients, stimulation with Tenascin-C induced greater MMP-1 expression by asthma patient ASM-derived cells, via JNK, p38, and ERK1/2 MAPKs signaling, and blocking β1 and β3 integrins decreased this response." (PMID 29988449, 2018).
asthma (continued). "To determine if this change in ECM expression by asthma derived ASM could be responsible for the enhanced MMP-1 secretion we generated ECM preparations from three control and five asthma derived ASM cultures." (PMID 24587395, 2014). "MMP-1 and tenascin-C are co-localised in the smooth muscle bundles of patients with asthma where this interaction may contribute to enhanced airway contraction." (PMID 24587395, 2014). "However, in patients with asthma, MMP-1 protein is present in the small airways and lung parenchyma." (PMID 24587395, 2014). "Our findings suggest that ECM changes in airway remodelling via MMP-1 could contribute to an environment promoting greater airway narrowing in response to broncho-constrictor stimuli and worsening asthma symptoms." (PMID 24587395, 2014). "Having shown that ECM proteins can induce the expression of MMP-1 by ASM, and that these proteins are co­localised in the airways of patients with asthma, we examined whether MMP-1 had functional consequences for airway contraction." (PMID 24587395, 2014). "Taken together, these findings suggest that, the induction of MMP-1 by abnormal ECM in the airways of patients with asthma may result in reduced airway stiffness, enhanced airway narrowing in response to bronchoconstrictor stimuli and worsening asthma symptoms." (PMID 24587395, 2014). "Elevated levels of MMP-1, MMP-2, MMP-8, and MMP-9 have also been found in the sputum and bronchoalveolar lavage fluid of patients with asthma and COPD." (PMID 40940719, 2025). "MMP-1 and MMP-9 expression was increased in the nasal tissues of smokers with asthma and CRS via real-time PCR and western blot." (PMID 31653934, 2019). "In the present study, we found a link (involving IL-17A, MMP-1, and MMP-9 expression) between cigarette smoke and neo-osteogenesis in AE with asthma and CRS." (PMID 31653934, 2019). "We used airway smooth muscle cells (ASM) and bronchial biopsies from control donors and patients with asthma to examine the regulation of MMP-1 by ECM in ASM cells and the effect of MMP-1 on ASM contraction." (PMID 24587395, 2014). "Previous work has suggested that pro-inflammatory cytokines including IL1β and TNFα and cyclic strain also induce MMP-1 expression in ASM and are likely to be of relevance to asthma." (PMID 24587395, 2014). "To determine if tenascin-C regulates MMP-1 in disease, we examined the expression of tenascin-C and MMP-1 in the airways from five control donors and seven patients with asthma." (PMID 24587395, 2014). "Of functional relevance to asthma, MMP-1, collagen-I and tenascin-C are co-located in the airways of patients with asthma and ASM derived MMP-1 facilitated the agonist induced ASM contraction in vitro." (PMID 24587395, 2014). "Asthma derived ASM invitro had higher basal expression levels of MMP-1 and upregulated MMP-1 expression in response to tenascin-C via a β3-integrin sensitive mechanism in common with normal cells." (PMID 24587395, 2014). "Increased levels of MMP-1, MMP-2, and MMP-9 have been reported in the sputum and lung parenchyma of asthma or COPD patients." (PMID 23226927, 2012). "KEGG functional analysis revealed that MMP1 was enriched in autoimmune thyroid disease and cell adhesion molecule cams, SAA1 was enriched in autoimmune thyroid disease and cell adhesion molecule cams, and PLAU was enriched in asthma and the citrate cycle." (PMID 39744064, 2024). "Taken together, these results reveal that cigarette smoking may have association with an IL-17A-mediated inflammatory response and increased MMP-1 and MMP-9 expression in the nasal mucosa of patients with asthma and CRS." (PMID 31653934, 2019). "As increased ECM deposition is a feature of airway remodelling in asthma, we hypothesised that asthma derived ASM may secrete increased levels of ECM proteins resulting in enhanced MMP-1 production by an autocrine mechanism." (PMID 24587395, 2014).
asthma (continued). "Furthermore, MMPs such as MMP-1 and -9 may be predictors of lower airway obstruction and resistance to contemporary steroid-based medical treatment in patients with CRS and asthma." (PMID 31653934, 2019). "Interestingly, in the non-atopic asthma group, FeNO, MMP-1, and CXCL9 all inter-correlated, whereas this was not seen in atopic asthmatics." (PMID 30834110, 2019). "Furthermore, in this group, airway responsiveness, asthma control, and asthma-related quality of life all associated with signs of non-type 2 inflammation, such as blood neutrophil count, CRP, HNL, IL-8, and MMP-1." (PMID 30834110, 2019). "In addition, MMP1 and THBS1 each connect two genes with potential role in severe equine asthma though not yet associated with asthma in humans or mice." (PMID 28886691, 2017). "We therefore examined the regulation of MMP-1 by the ECM proteins which are differentially expressed in remodelled airways and whether the resulting increase in MMP-1 activity could functionally contribute to the asthma phenotype." (PMID 24587395, 2014). "Hypoxia, which is associated with extracellular matrix remodeling in inflammatory lung diseases, such as fibrosis, COPD, and asthma, upregulated the expression of MMP-1, MMP-2, and MMP-9 precursors without subsequent activation in human lung fibroblasts and pulmonary vascular smooth muscle cells." (PMID 23226927, 2012). "Our results revealed the expression of MMP-1, MMP-9 in the nasal tissues, and maximal AE bone thickness on CT scans were greater in smokers with asthma and CRS than in asthmatic non-smokers with CRS and asthmatic non-smokers without CRS." (PMID 31653934, 2019). "Protein analyzed by western blotting confirmed the results of mRNA and revealed that smokers with CRS and asthma had higher levels of MMP-1 (P = 0.032) and MMP-9 (P = 0.042) expression than those of non-smokers with CRS and asthma." (PMID 31653934, 2019). "Tenascin-C and MMP-1 were not expressed in normal airways but co-localised in the ASM bundles and reticular basement membrane of patients with asthma." (PMID 24587395, 2014). "The mRNA expression of MMP-1 (P = 0.043) and MMP-9 (P = 0.003) was significantly up-regulated in the nasal tissues of smokers with CRS and asthma compared to those of non-smokers with asthma and CRS." (PMID 31653934, 2019). "The absence of tenascin-C in control tissue, deposition in asthma and proximity to MMP-1 expression denote tenascin-C as a potential, pathologically-relevant, regulator of MMP-1 expression in vivo and target for therapeutic intervention against airway remodelling." (PMID 24587395, 2014).